CD4 (CD4 molecule)
Diseases named in the same sentence as CD4 in open-access papers (continued):
Sharing a sentence is not in itself a finding about the gene and the disease.
Autoimmunity (continued). "Despite the much enhanced capacity of IFN-γ production by CD4+ T cells and a significant increase of CD44hiCD62L- activated T cells, Cd11c-p28f/f mice displayed no apparent signs of autoimmunity under steady-state conditions." (PMID 40366856, 2025). "Further studies on the role of CD4+ T-cells in the development of SLE and autoimmunity could, therefore, lead to the identification of new therapeutic targets for SLE." (PMID 40429614, 2025). "OX40 is a ligand-activated T-cell co-stimulator that mediates the survival and expansion of CD4+ and CD8+ T cells in a variety of animal models of autoimmunity, infectious disease, and cancer, and is also involved in the control of effector and memory T-cell responses." (PMID 40356928, 2025). "Conversely, recent research has demonstrated that an elevated histone H3 lysine 27 trimethylation enrichment at the promoter of haematopoietic progenitor kinase 1 (HPK1) in SLE CD4+ T cells (in comparison to controls) suppresses HPK1 expression and has a role in promoting autoimmunity in SLE." (PMID 40976999, 2025). "Trying to put the different events into a trajectory leads us to propose an initial immune dysregulation and systemic autoimmunity in mucosal surfaces, a second hit involving both CD8+ and CD4+ T cells, involving HLA-specific interactions of autoreactive cells resulting in joint targeting responses." (PMID 40639878, 2025). "Overall, the absence of PD‐1 in a small proportion of CD4+ T cells can greatly impact inflammation and autoimmunity in NOD mice." (PMID 40623940, 2025). "CD4+CD25+ cells displayed an acceleration of complex-type synthesis in the HT1 group, which was normalized in HT2 donors, representing the advanced stage of autoimmunity." (PMID 41030447, 2025). "While CD4+ Treg cells have been extensively studied, their CD8+ counterparts remain far less understood, although their potential contribution to the therapy field of autoimmunity makes them an ideal candidate to explore." (PMID 41226379, 2025). "Patients with primary antibody deficiencies and autoimmunity had fewer counts of CD3+ and CD4+ T cells than those without autoimmunity." (PMID 39836840, 2024). "In conclusion, regardless of the importance of CD4+CD25+ T cells in autoimmunity onset, none of these models provided evidence of the permanence of Treg suppression." (PMID 38404584, 2024). "To further evaluate risks of autoimmunity and inflammation, we evaluated the rate of divisions of conventional CD4+ T cells and RAG1-/- cells in vivo, and found no increase in ASO FOXP3 treated group." (PMID 39234236, 2024). "Interleukin 2 is secreted by activated T lymphocytes (both CD4+ and CD8+) and plays an important role in the proliferation of T and B lymphocytes by inducing effector T lymphocytes as well as generating Tregs that can prevent autoimmunity." (PMID 39015324, 2024). "Non-depleting anti-CD4 therapy has been shown to suppress autoimmunity and graft rejection by modulating the function of CD4+ T cells by blocking T cell activation and promoting Treg differentiation and suppressor functions." (PMID 39759532, 2024). "CXCR3 binds and traffics toward its IFNγ-inducible ligands, CXCL9, 10, and 11, which are expressed primarily in activated CD8+ T cells, NK cells, and CD4+ TH1 cells and play critical roles in recruiting and retaining T cells during infection, autoimmunity and cancer." (PMID 39409972, 2024). "Specifically, inhibition of BH4 synthesis in vivo reportedly abolishes T cell-mediated autoimmunity and allergic inflammation, whereas GCH1 overexpression increases BH4 levels, leading to increased responses by CD4- and CD8-expressing T cells and enhanced antitumor activity in vivo." (PMID 39723384, 2024). "Phenotypic changes in the CD4-lineage populations of Sin3a−/−CD4cre mice likely explain why they did not develop fatal autoimmunity like Sin3a−/−Foxp3cre mice despite having dysfunctional Tregs." (PMID 39156895, 2024).
Autoimmunity (continued). "Conversely, administration of CD25-blocking monoclonal antibody daclizumab led to significant and prolonged decrease in peripheral CD25+FOXP3+CD4 T cells in patients with metastatic breast cancer in the absence of autoimmunity." (PMID 39232704, 2024). "If the main role of TβRIII is to function as a co-receptor for TβRI and TβRII, we would expect mice lacking TβRIII on CD4+ T cells to also exhibit spontaneous autoimmunity and death." (PMID 36855628, 2023). "By 9 weeks of age, Stat1T385M/+ mice showed expansion of MP CD4 cells expressing Tfh-like markers, in spleen and in gut-draining mLN, with no observed autoimmunity." (PMID 37275873, 2023). "Here we assay gene expression between T1D cases and healthy controls in two autoimmunity-relevant lymphocyte cell types, memory CD4+/CD25+ regulatory T cells (Treg) and memory CD4+/CD25- T cells, using a splicing event-based approach to characterize tissue-specific transcriptomes." (PMID 37758901, 2023). "The evolutionary presence of CD4+ T cells alongside B and CD8+ T cells emphasize their critical role in enhancing immune responses against pathogens while protecting against allergies and autoimmunity." (PMID 37892982, 2023). "CD4+ T cells expressing FOXP3 are thought to promote immune tolerance in β-cells and, therefore, increased levels of FOXP3+ CD4+ T cells signify a reduction in autoimmunity." (PMID 37400916, 2023). "Both CD4+ and CD8+ T cells produce IL-17A and play important roles in autoimmunity." (PMID 36817487, 2023). "Finally, Nectin-family ligands are differentially expressed in NK cells, B cells and CD4+ and CD8+ T lymphocytes during chronic inflammation and autoimmunity." (PMID 36979144, 2023). "Hence, the immunological mechanism of autoimmunity occurs as follows: First, after SCI, these autoantigens are exposed, and after antigen presentation by antigen-presenting cells (APCs), CD4+ T cells convert into effector CD4+ T cells." (PMID 37291666, 2023). "The presence of specific antigens on the prostate tissue allows CD4+ CD25- T cells in the humoral fluid to recognize and induce autoimmunity on the one hand and promotes the production of prostate tissue-specific suppressor T cells to tolerate the immune response on the other." (PMID 37228599, 2023). "When CD4+ T cell help is absent, dysfunctional, or hyperactive, this delicate balance is thrown off, leading to increased infections, autoimmunity, or allergies." (PMID 37892982, 2023). "In autoimmunity, PD1 is involved in rheostatic modulation of T cell receptor (TCR) signaling that prevents the development of autoreactive T cells and the following tissue destruction, and PD1 expression in CD4+ and CD8+ T cells is increased." (PMID 37707595, 2023). "Flowcytometry revealed reduced proportion of CD4+CD25HIGHFOXP3+ Tregs in patients with CVID with autoimmunity as compared to patients with CVID without autoimmunity." (PMID 35795667, 2022). "CXCR3 is involved in the direction of CD4+ and CD8+ T-cells in context of cancer and autoimmunity." (PMID 36157879, 2022). "CD4+CD25+ regulatory T cells (Tregs), a subpopulation of naturally CD4+ T cells that characteristically express transcription factor Forkhead box P3 (FOXP3), play a pivotal role in the maintenance of immune homeostasis and the prevention of autoimmunity." (PMID 35474948, 2022). "The regulatory mechanism that BCL6 could be transactivated by STAT1 was also observed in imatinib-treated chronic myeloid leukemia cells and contributed to CD4+ T follicular helper cell TFH differentiation and autoimmunity." (PMID 35503721, 2022). "Central to the impacts of CD4 T cells, both positive in settings of infectious disease and cancer and negative in the settings of autoimmunity and allergy, is their ability to differentiate into distinct effector subsets with specialized functions." (PMID 36358898, 2022).
Autoimmunity (continued). "Control of effector T cell responses by NK cells has been observed in the context of infection and has been suggested in autoimmunity, but direct evidence for NK cells affecting autoreactive myelin-specific CD4+ cells has not been described." (PMID 35587373, 2022). "When pDCs are chronically activated, they produce sustained levels of IFN-I that lead to negative consequences, such as CD4 T cell depletion in HIV-infected patients or the promotion of autoimmunity by promoting skin lesions." (PMID 36083891, 2022). "Systematically increased sCD25 may indicate higher protease activity, and low regulatory capacity of CD4+/CD25+ Treg cells, thus further supporting autoimmunity." (PMID 35337097, 2022). "V-Domain Ig Suppressor of T Cell Activation (VISTA) is expressed on several immune cells, including CD11b+ myeloid cells, naïve CD4+ and CD8+ T cells, CD4+ Foxp3+ Treg cells, and TCRγδ T cells, and negatively regulates T cell-mediated autoimmunity and antitumor immunity." (PMID 36514901, 2022). "Dual IFNγ and IL-17 producing CD4+ Th cells called Th17.1, non-classic Th1, and ex-Th17 cells are identified in various autoimmune conditions, often at sites of inflammation." (PMID 35860254, 2022). "In the CVID with autoimmunity group, absolute counts of total CD19+ B cells, total CD4+ Th cells, and naive CD4+ Th cells were lower than in the group without autoimmunity, but this difference was not significant." (PMID 35402361, 2022). "If not adequately regulated, CD4+ T cells can be also involved in autoimmunity, asthma, and other allergic responses." (PMID 36555219, 2022). "Treg cells are CD4+CD25+ T lymphocytes that exert a negatively immune regulation function, and they secrete various immunoregulatory factors, which prevent the acute inflammatory responses of effector cells and play a critical role in maintaining autoimmunity." (PMID 36327403, 2022). "This is a subset of CD4+CD25+ T cells expressing the transcription factor Forkhead box P3 (Foxp3), which could suppress spontaneous multi-organ autoimmunity, including gastrointestinal inflammation induced by CD4+CD25− T cells." (PMID 36076980, 2022). "In this review, we have primarily focused on the characteristics of CD4 Tregs and new players of the regulatory club and their changes in patients with CVID in relation to autoimmunity and emphasized the complexity of interplay among various regulatory lymphocytes." (PMID 35669770, 2022). "When STAT3 is genetically deleted in CD4+ T cells, neither naturally occurring Th17 cells nor Th17-dependent autoimmunity occurs." (PMID 36033859, 2022). "To investigate the reason for the decrease in EAE signs in the Tg + EAE group, we investigated the infiltration and proliferation of CD4+ and CD8+ T cells and resident inflammatory immune cells (microglia and astrocytes) as an autoimmunity-related cell population." (PMID 33205383, 2021). "DCs predominantly activate CD4+ T helper cells, which ensure the amplification of T cell response without deleterious autoimmunity." (PMID 34277389, 2021). "In autoimmunity, cDC1s are involved in cross-presentation of antigen to CD8+ T cells while cDC2s present antigen to CD4 and may be more tolerogenic by promoting expansion of Tregs." (PMID 34747368, 2021). "The extraordinarily long-term protection against autoimmunity by a single cohort of self-renewing Treg cells suggests that these cells do not exhibit dysfunction typical of chronically stimulated CD4 and CD8 T cells." (PMID 34426690, 2021). "Thirdly, we have found that patients with 18q deletions, irrespective of their autoimmune or allergic status, had CD4+CD25+FOXP3+ Treg cell deficiency—the key players controlling reactivity to self-antigens and preventing autoimmunity." (PMID 34867966, 2021).
Autoimmunity (continued). "In addition, we also find that miR‐21 sustains the differentiation in vitro of naïve CD4 T cells into potentially pathogenic TH17 cells, while it restrains their differentiation into iTregs, promoting conditions that could favour and/or sustain chronic inflammation and autoimmunity." (PMID 34584693, 2021). "Of note that reduced frequencies of activated CD8+ and CD4+ T effector cells do not support autoimmunity progression." (PMID 34539667, 2021). "We show for the first time that LIFNano-CD4 (i) cross the BBB; (ii) reduce pathogenic levels of IL-6 that accumulate behind the BBB during demyelinating autoimmunity; and (iii) are non-toxic at efficacious i.v. doses in a formal preclinical SAD trial." (PMID 35047909, 2021). "Both B-cells and T-cells, including CD4+ and CD8+ T-cells, as well as other T-cell subsets, could affect onset of autoimmunity." (PMID 32802890, 2020). "Furthermore, mice that lack miRC-1 in CD4+ T cells have reduced TH17 differentiation and effector function, and are protected from autoimmunity and severe colitis." (PMID 32155783, 2020). "nTregs arise from CD4+ single positive thymocytes, leave the thymus as FOXP3+ nTregs, and are enriched for T cell receptors (TCRs) that have a high affinity for self-peptides, thus playing an important role in autoimmunity." (PMID 32977677, 2020). "CD4+CD25+Foxp3+ Tregs that develop in the thymus constitute 2–4% of CD4 single positive thymocytes, yet this relatively small population plays a critical role in maintaining peripheral tolerance and preventing autoimmunity." (PMID 32646440, 2020). "Besides the ensuing CD4+ T-cell reduction, HIV infection has been shown to alter the mechanisms of immunological tolerance and autoimmunity in HIV-positive patients." (PMID 33324890, 2019). "Reportedly, mice with reduced Foxp3 expression in Tregs developed multiorgan autoimmunity when Tregs also lacked PD-1 expression, suggesting that PD-1 inhibition non-redundantly controls an additional pool of autoreactive CD4+ cells." (PMID 31653839, 2019). "In the absence of autoimmunity, the phenotype of recipient-derived CD4+ Foxp3+ T cells from CD25cKO mice largely resembled the immature Tregs from their thymus." (PMID 30833563, 2019). "The colorectal cancer antigen GUCY2C exhibits unique split tolerance, evoking antigen-specific CD8+, but not CD4+, T-cell responses that deliver anti-tumor immunity without autoimmunity in mice." (PMID 31010434, 2019). "CD4/CD28 null, a unique subset of CD4 cells, is present in low frequencies in healthy individuals and increased in patients with chronic inflammatory diseases such as autoimmunity." (PMID 31565659, 2019). "CD4+ CD25+ Foxp3+ regulatory T cell (Treg), another subtype of CD4+ T cell, is essential for preventing autoimmunity and maintaining lymphocyte homeostasis by contacting or releasing inhibitory cytokine like IL-10 and TGF-β on other immune cells during chronic inflammatory disease." (PMID 30800170, 2019). "Although CD4+CD25+FoxP3+ Tregs are a major subset of Tregs, mounting evidence has shown that CD8+CD122+ T cells also are Tregs that suppress T cell responses and autoimmunity." (PMID 30863408, 2019). "Within CD4+ T cells, autoimmunity in CVID was particularly associated with reduced number of regulatory T cells (TR) compared to CVID patients without autoimmunity." (PMID 31921101, 2019). "CD4+ IFN-γ cells are important for T helper (Th1) immunity and prevents autoimmunity." (PMID 30166607, 2018). "In this work, we focus in the population of CD4+CD25+ T cells and CD4+CD25+FOXP3+ T cells (considered to be part of Treg cells classification), given that these cells play key roles in self-tolerance and autoimmunity." (PMID 29928277, 2018). "The existence of self antigen-specific resident CD4 Treg cells within the LNs of SPF and germ-free mice makes sense, since such cells would protect the drained organs from efficient priming of conventional self-reactive T cells, thus preventing autoimmunity." (PMID 29302034, 2018).
Autoimmunity (continued). "Taken together, our data suggest that even in a lymphoreplete adult host, peripheral newly generated T cells retain a heightened potential for LIP-driven autoimmunity in the absence of PD-1, which is mediated by CD4 T cells." (PMID 29416537, 2018). "In the mouse, a lack of CD4+ Foxp3+ Tregs results in increased autoimmunity, and adoptive transfer of Tregs prevents and reverses autoimmunity." (PMID 30037796, 2018). "Overall, data presented in this study indicates that CD8+HLA-DR+ Treg and CD4+FOXP3+ Treg share phenotypic and functional features, and that they may be similarly involved in the control of antitumor immune responses and autoimmunity." (PMID 30555473, 2018). "The safety and lack of autoimmunity secondary to CD4-AsiC knockdown of PITPNM3 or antibody inhibition of CCL18, PITPNM3 or CCR8 will need to be examined carefully to evaluate potential therapeutic applications." (PMID 28290464, 2017). "In the mouse, a lack of CD4+ FoxP3+ Tregs resulted in increased autoimmunity, and adoptive transfer of Treg prevented and reversed autoimmunity." (PMID 28621034, 2017). "Altogether, the deviation of autoimmunity from the pancreas to skeletal muscles in the absence of ICOS/ICOSL signaling in NOD mice is strictly dependent on CD4+ T-cells, leads to myofiber necrosis and regeneration." (PMID 28424681, 2017). "CD4+ CD25+ Treg cells are involved in the suppression of the autoreactive T cells by producing anti-inflammatory cytokines, IL-10 and TGF-ß and suppressing the organ specific autoimmunity." (PMID 28661456, 2017). "Immunosurveillance by CD4+ CD25+ Foxp3+ T cells, CD8+ T cells, γδ T cells, and NK/NKT cells present within the CALT of healthy subjects may provide protection against autoimmunity." (PMID 28661456, 2017). "Chief among these is to more specifically define the roles of CD4 and CD8 T cells and to determine whether autoimmunity or alloimmunity represents the higher barrier to beta cell transplant survival." (PMID 29259578, 2017). "The resulting cMy-mOVA-OT-II mice did not display signs of spontaneous autoimmunity despite the fact that their OVA-specific CD4+-T cells were not anergic." (PMID 29167489, 2017). "In addition, I3C and indirubin increase the number of CD4+CD25+ Tregs and suppress chronic inflammatory diseases and/or autoimmunity in vivo." (PMID 27445434, 2016). "Because low CCR7 and high PD-1 expression have been observed in circulating TFH from patients with autoimmune conditions, we examined the TFH subsets considering the level of expression of these molecules on the surface of CXCR5+CD4+ T cells from CVID patients and N controls." (PMID 27069935, 2016). "Since CD8+ T cells have a higher expression of VDR than CD4+ T cells, CD8+ T cells may also be a target for 1,25(OH)2D3 in the suppression of autoimmunity." (PMID 28163705, 2016). "Recent studies in inflammatory arthritis have identified CD4+CD25+CD161+ T cells as the IL-17-producing Th17-like Treg cells, which showed decreased suppressive activity and might contribute to autoimmunity in inflammatory sites." (PMID 26436101, 2015). "CD4+ and CD8+ are two subtypes of T lymphocytes which usually maintain a stable ratio under normal conditions, and often, increases or decreases in this ratio is indicative of autoimmune disorders." (PMID 26086781, 2015). "InsB9-23/IFA immunization significantly prolonged syngeneic pancreatic islet survival in NOD mice by a mechanism that necessitated the presence of CD4+CD25+ T regulatory (Treg) cells, while combination of three islet epitopes was less efficacious in controlling recurrent autoimmunity." (PMID 26080071, 2015). "CD4+CD8+ cells are a normal finding in the thymus; they can be present in the circulation in healthy individuals and at a higher proportion in some diseases, e.g., autoimmune conditions." (PMID 25853009, 2015).